SNAI1 (snail family transcriptional repressor 1)
Diseases named in the same sentence as SNAI1 in open-access papers (continued):
Sharing a sentence is not in itself a finding about the gene and the disease.
cancer (continued). "SNAI1-induced EMT in cancer cells promotes a more fibroblast-like appearance and increases the invasive behavior by suppressing CDH1 and β-catenin expression through elevated vimentin expression." (PMID 34455105, 2021). "TOX high mobility group box family member 3-like (TOX3) in the spleen has been shown to inhibit the proliferation and migration of cancer cells by transcriptional regulation of SNAI1 and SNAI2 to prevent disruption of the epithelial cell layer." (PMID 34135900, 2021). "EMT of cancer cells accompanied with Snail homolog 1 (SNAI1) overexpression up‐regulates BECN1, leading to increased autophagy." (PMID 33605033, 2021). "GLI proteins upregulate the expression of invasion-related and mesenchymal proteins, such as matrix metalloproteinases, N-cadherin, vimentin, and SNAI1, to activate cancer migration, invasion, and metastasis." (PMID 34572373, 2021). "The metastatic process is fuelled by inflammation, a hallmark of cancer, leading to the activation of canonical NF-κB, a major regulator of pleiotropic EMT-inducing transcription factors (EMT-TFs), such as Snail/SNAI1, Slug/SNAI2 and Twist." (PMID 34503110, 2021). "We demonstrate on the molecular level that SNAI1 binds promoters of let-7 family members in cancer cells." (PMID 33806868, 2021). "For example, we used EMTome to perform sample-level immune abundance enrichment for TCGA cancer type and correlated with SNAI1 expression." (PMID 33299129, 2021). "We previously showed that, in a cancer model, Rreb1 directly binds to the regulatory region of Snai1 in cooperation with TGF-β activated SMAD transcription factors to induce the expression of SNAIL, which drives EMT." (PMID 33929320, 2021). "SNAI1 knockdown leads to decreased stemness and the restoration of let-7 expression in cancer cells, including patient-derived cells." (PMID 33806868, 2021). "The increased expression of SNAI1, TWIST, and ZEB1 is thought to be associated with the acquisition of the cancer stem cell (CSC) phenotype, high metastatic potential, and increased resistance to chemo- and radiotherapy." (PMID 34683705, 2021). "Because of their critical roles in cancer metastasis, much attention has focused on the PTMs of SNAI1." (PMID 34681726, 2021). "Of these three DUBs, USP37 binds SNAI1 most strongly and plays a major role in stabilizing SNAI1 and thereby promoting cancer cell migration, E cadherin downregulation, and vimentin upregulation." (PMID 34758854, 2021). "Exosomes derived from gemcitabine-treated CAFs contain SNAI1 and support the growth and survival of exosome-receiving cancer cells." (PMID 32756339, 2020). "Here, we report that the expression and prognosis of six key EMT-related genes in cancer, and found high SNAI1 expression was closely related with poorer overall survival in gastrointestinal cancers, and was validated in GEO database." (PMID 32833672, 2020). "Our study provides further evidence that acetate and its derivative, acetyl-CoA, play an important role in expression of SNAI1 and cancer cell migration." (PMID 32458971, 2020). "Cancer with bone metastasis showed estrogen receptor and SNAI1 over-expression; cancer with liver metastasis showed SNAI1 over-expression; and cancer with lung metastasis showed EGFR, CK5 and HER2 protein over-expression." (PMID 33369456, 2020). "As SNAI1 is a well-characterized downstream gene of c-Myc, the possible functional role of the PCGEM1/c-Myc/SNAI1 signaling axis in hypoxia-associated cancer progression warrants further investigation." (PMID 32370770, 2020). "Accordingly, genetic depletion and CRISPR-mediated gene knockout of STAMBPL1 leads to marked recovery of epithelial markers, SNAI1 destabilisation and impaired migratory capacity of cancer cells." (PMID 32636467, 2020).
cancer (continued). "FIRΔexon2 acetylated H3K27 on promoter of BRG1 by CHIP-sequence and suppressed BRG1 expression post-transcriptionally; herein BRG1 suppressed Snai1 that is a transcriptional suppressor of E-cadherin that prevents cancer invasion and metastasis." (PMID 32071290, 2020). "Both EMT and cancer metastasis are stimulated by an increase in SNAI1, N-cadherin, Zeb1, and vimentin, and a decrease in E-cadherin." (PMID 30736337, 2019). "As a result, autophagy-induced SNAI1 degradation in the cytoplasm inhibits SNAI1 translocation into the nucleus and blocks the transcription of many genes involved in cancer cell invasion and migration." (PMID 30736337, 2019). "In contrast, blocking autophagy with chemicals or by gene silencing increases SNAI1 protein levels and leads to normal cancer progression." (PMID 30736337, 2019). "For example, Hedgehog signaling, which is aberrantly activated in several types of cancers, linked Wnt signaling pathways with cell survival genes BCL2 and EMT driver genes SNAI1/2, ZEB1/2 through epigenetic or genetic alterations during carcinogenesis." (PMID 30548372, 2019). "In this study, we show a similar decrease in SNAI1, N-cadherin, and Zeb1 upon starvation-induced autophagy in two cancer cell lines." (PMID 30736337, 2019). "During EMT and cancer metastasis, the levels of proteins such as N-cadherin, Zeb1, and vimentin significantly increase while the amount of E-cadherin decreases due to SNAI1-dependent transcriptional regulation." (PMID 30736337, 2019). "SNAI1, which is a master regulator of epithelial-to-mesenchymal transition, has shown to be overexpressed in several cancer cells and is often related to prognosis and aggressiveness." (PMID 31014274, 2019). "FLG interacts with MCL1, USP1, C21orf59, MAK, and KIR3DS1 and mucin interacts with ERBB3, SNAI1, TWIST1, TWIST2, and CDH2, all of which, IPA predicted to be associated with cancer." (PMID 31058088, 2019). "Based on these results, we suggest that intracellular SNAI1 protein levels are controlled by autophagy during cancer progression, which is consistent with results from previous studies in which autophagy inhibited cancer growth by degrading SNAI1." (PMID 30736337, 2019). "In development and cancer, Snai1 expression typically precedes and helps induce the expression of other EMT TFs including Zeb159–61, and thus it is interesting that in our system Zeb1 can induce Snai1, perhaps through indirect mechanisms." (PMID 30405106, 2018). "Activation of both AKT and NF-κB would result in increased Snai1 expression, which in turn has been shown by several groups to confer drug resistance to cancer cells." (PMID 30034631, 2018). "High expression of both SNAI1 and PDGF receptors is associated with poor prognosis in cancer patients, but the mechanism(s) that underlie these connections are not understood." (PMID 30250018, 2018). "Transduction of oncogenic KRAS dramatically enhances TGF-β-elicited SNAI1 expression, and TGF-β induces SNAI1 more strongly in cancer cells harboring constitutively active KRAS mutations." (PMID 30127261, 2018). "In the context of cancer, Snail (SNAI1) was identified as the first EMT‐TF that directly repressed transcription of the epithelial cell–cell adhesion molecule, E‐cadherin." (PMID 28548345, 2017). "It has been reported that LSD1 is essential for Snai1-mediated transcriptional repression and for maintenance of the silenced state of Snai1 target genes in invasive cancer cells." (PMID 26821054, 2016). "The distinct effects of Rho inhibition on cancer cell invasion has been related to the expression of its different isoforms and the activity of the zinc-finger transcription factors Snai1 and Snail2." (PMID 27549189, 2016). "The Wnt pathway, often deregulated in cancer, leads to induction of SNAI1 expression with subsequent downregulation of E-cadherin via β-catenin." (PMID 27429011, 2016).
cancer (continued). "Zeb1/2, Snai1/2 and Twist1 have recently been described as targets of the Fbxo45 containing ubiquitin ligase complex in cancer cell lines." (PMID 26068074, 2015). "SNAI1 has also been reported to increase the expression of mesenchymal markers Vimentin and Fibronectin as well as other proteins involved in cancer invasion such as metalloproteinases 2 and 9, and various transcription factors such as ZEB-1 and LEF-1." (PMID 24565133, 2014). "But it should be cautioned that SNAI1 plays an important role during embryonic development and is also considered an important stem cell regulator, therefore SNAI1 inhibitors should be specifically targeted towards cancer cells." (PMID 24565133, 2014). "SNAI1 is overexpressed in several cancer cells including PCA where it is suggested to be upregulated at early stages of PCA development." (PMID 24565133, 2014). "The Snail family of transcription factors that includes Snail (SNAI1), Slug (SNAI2), and Smug is involved in physiological and cancer-associated EMT." (PMID 23799116, 2013). "More relevantly, both Snai1 and Snai2 have exhibited migratory and anti-apoptotic functions when studied in cancer models." (PMID 23874916, 2013). "SNAI1 can initiate epithelial-mesenchymal transition (EMT), leading to loss of epithelial characteristics and, in cancer, to invasion and metastasis." (PMID 20181105, 2010). "Aberrant expression of SNAI1 and SNAI2 is also linked to cancer metastasis in epithelial cell lines through its role in directing epithelial-to-mesenchymal cell transition (EMT)." (PMID 20046880, 2009). "Both the transcription factor SNAI1 and the PA system influence cancer cell migration and are over-expressed in cancers." (PMID 19055748, 2008). "SNAI1, a gene implicated in epithelial to mesenchymal transition with roles in cancer development and progression, was not consistently upregulated." (PMID 40470201, 2025). "Snai1 is activated by ROS, leading to enhanced cancer progression." (PMID 40497987, 2025). "Underlying these processes, cancer cells overexpressing FSTL3 exhibited increased expression of the genes associated with epithelial-mesenchymal transition (Vim, Zeb-1, Snai1/2) and extracellular matrix organization (Ecm1), while expression of epithelial markers (Epcam, Cdh1) decreased." (PMID 41029436, 2025). "In conclusion, these findings suggested that VRK1/CHD1L/SNAI1 axis acts as a cancer-driving pathway to promote the proliferation and EMT of HCC, indicating that targeting VRK1 may be an attractive therapeutic strategy of HCC." (PMID 40234378, 2025). "Specifically, expression changes in SNAI1, CD44 and ALDH1A3 genes were positively associated with the viable cancer cell fraction (rs > 0.5 and p < 0.05), suggesting that PDS cultures promoting CSC features might be less susceptible to T cells action." (PMID 40240529, 2025). "Snai1 activation by reactive oxygen species (ROS) contributes to the advancement of cancer." (PMID 40497987, 2025). "Given that M2 macrophages are known to induce epithelial‐mesenchymal transformation (EMT) in cancer cells, we explored the correlation between VSIG4 and several biomarkers associated with EMT processes (MMP9, SNAI1, SNAI2, VIM, TWIST1, TWIST2, CDH1, CDH2) in CRC through the TIMER2.0 website." (PMID 40405491, 2025). "Notably, Snai1 upregulates the expression of Zeb family proteins in carcinoma cells by inducing the expression of a natural antisense transcript for ZEB2 (NAT)." (PMID 40134588, 2025). "We integrated analyzed the function of P4HA3 among 33 types of cancers, and found that P4HA3 was associated with proliferation markers (PCNA and MKI67), EMT markers (VIM, TWIST1, SNAI1, SNAI2, FN1 and CDH2), extracellular matrix (ECM) markers (MMP9, MMP7, MMP2 and MMP14)." (PMID 39504328, 2024). "The differentiation status of cancer cells was also closely related to SNAI1 expression." (PMID 39702326, 2024). "Furthermore, we observed that the overexpression of SNAI1 sustained cancer stem cell-like properties." (PMID 39702326, 2024).
cancer (continued). "As a key regulator of epithelial-mesenchymal transition, SNAI1 has been reported to be crucial for the progression of cancer, in respect to its functions such as enabling resistance to anti-cancer drugs or facilitating invasion by cancer cells." (PMID 38671227, 2024). "Given that CSCs are reported to stimulate M1 to M2 macrophage polarization, the administration of rosiglitazone, by suppressing SNAI1 expression and inhibiting cancer stemness, could potentially reverse this polarization." (PMID 39702326, 2024). "In this study, we demonstrated that Snai1 is upregulated in the vascular endothelium of carcinomas." (PMID 39095583, 2024). "For Snai1, expression in tECs could be verified in immunohistologically stained sections of various carcinomas." (PMID 39095583, 2024). "SNAI1 has also been observed to be upregulated in hepatocellular carcinoma and ovarian carcinoma amongst several other cancer types, indicating its vital role in cancer progression, and its significance for prognostic and diagnostic tools in cancer research." (PMID 36980876, 2023). "ROS have been shown to regulate numerous signalling pathways (e.g., the MAPK and PI3K/AKT pathways) and activities of key transcriptional factors (e.g., hypoxia-inducible factor (HIF) and zinc finger protein SNAI1 (SNAI1)) to enhance cancer cell migration and invasion." (PMID 36701089, 2023). "Previous studies have reported abnormal expression of SNAI1 in various malignant tumors." (PMID 35300562, 2022). "Of note, while YBX1 promotes cancer cell proliferation and survival in many cancer types, it functions primarily to enhance metastasis in ccRCC, consistent its role in translational activation of Snai1 in ccRCC cells." (PMID 36028903, 2022). "Tumorigenicity and invasiveness are important acquired characteristics for the development and progression of cancer, and could be regulated by transcription factors associated with EMT, such as ZEB1, ZEB2, SNAI1, SLUG, and STAT3." (PMID 35723302, 2022). "Moreover, upregulation of the zinc finger protein SNAI1 (SNAIL1) transcription factor is necessary for anastasis of cancer cells, which stimulates EMT through inhibition of E-cadherin synthesis." (PMID 35659306, 2022). "Recently, the relationship between SNAI1 and miRNAs is reported in various cancers." (PMID 35912006, 2022). "Notably, we confirmed this finding in the individual example of PHF13-bound and TGFβ-activated gene SNAI1, whose expression was dependent on PHF13 and highly associated with cancer metastasis." (PMID 35597793, 2022). "Furthermore, PHF13-dependent chromatin regions are enriched in broad H3K4me3 domains and super-enhancers, which control genes critical to cancer-cell migration and invasion, such as SNAI1 and SOX9." (PMID 35597793, 2022). "SNAI1 is a zinc finger transcription factor and functions as a driver of cancer progression." (PMID 35912006, 2022). "In addition, overexpression of EMT-TFs, e.g., Twist1, Zeb1, or Snai1, can also confer the stem cell traits to normal and transformed epithelial cells as well as cancer cells 19,53-55." (PMID 36276640, 2022). "Overexpression of SNAI1 and TWIST1, encoding key regulators of epithelial-to-mesenchymal transition (EMT), significantly contributes to cancer development and has been directly related to chemoresistance and poor prognosis in several cancer types." (PMID 36140779, 2022). "Hence, we analyzed TCGA expression data from 32 cancer types (∼9,000 patient samples) to identify LncRNAs associated with EMT markers, VIM, FN1, SNAI1, SNAI2, and CDH1 (and material and method)." (PMID 36120580, 2022). "However, we focused on the detection of the periostin POSTN and transforming growth factor beta-induced protein TGFBI proteins, which, in cancer cells, are regulated by the stem cell transcription factor Snail (SNAI1)." (PMID 33806753, 2021). "Of note, few reported studies have shown that JNK regulates SNAI1 expression in cancer cells." (PMID 33510281, 2021).
cancer (continued). "Likewise, a number of studies demonstrated that PI3K/Akt signaling is indeed one of the regulators of SNAI1, particularly in other types of cancer." (PMID 34207850, 2021). "We predict that SNAI1-mediated let-7 repression could be an important mechanism of cancer stemness in a wide variety of carcinoma cells." (PMID 33806868, 2021). "In patients with advanced BCs in advanced stage (TNM III and IV), downregulated miR-203a-3p, and SNAI2 with ZEB1 were detected in TU-C and TU-IF, and upregulation of SNAI1 and miR-205-5p was found in samples with disseminated cancer cells, LNM and CD45-DB fractions, respectively." (PMID 35008529, 2021). "In conclusion, the SNAI1/let-7 axis is an important component of stemness pathways in cancer cells, and this study provides a rationale for future work examining this axis as a potential target for cancer stem cell-specific therapies." (PMID 33806868, 2021). "Next, we sought to compare our RPE-EMT proteome with the SNAI1-induced cancer EMT proteome." (PMID 34455105, 2021). "In addition, we also discovered that SNAI1 overexpression changes cancer cells’ cytoskeleton structure by inducing TUBB3 upregulation and specific compartmentalisation in the early stages of metastasis in colon cancer cells." (PMID 34073413, 2021). "Because AKT and ERK are well-established activators of SNAI1 expression in cancer cells, we tested whether they regulate the drastic elevation of SNAI1 levels in TN-resistant TNBC cells." (PMID 33510281, 2021). "Moreover, we describe recent insights into the epigenetic mechanisms of SNAI1-induced cancer metastasis, focusing on the cooperation of SNAI1 with epigenetic regulators." (PMID 34681726, 2021). "For example, EMT-TFs such as Snai1/2 and Twist1 also regulate cancer cell survival and cancer drug resistance, and it is currently unknown whether cell survival and drug resistance are regulated independently of EMT." (PMID 32300252, 2020). "The EMT-TF SNAI1 has been shown to have a strong impact on the cancer-immunity cycle." (PMID 35582229, 2020). "In this study high SNAI1 expression was found in 8 types of cancer." (PMID 32833672, 2020). "Furthermore, we suggest that targeting autophagy-dependent SNAI1 degradation is a promising strategy for the development of cancer therapies." (PMID 30736337, 2019). "Consistent with it, cancer tissue samples showed higher mRNA levels of SNAI1." (PMID 30770779, 2019). "To investigate whether autophagy-induced SNAI1 degradation influences the migration and invasion of cancer cells, we performed scratch assays under different conditions." (PMID 30736337, 2019). "In this study, we suggest that SNAI1 directly binds to LC3 in cancer cells." (PMID 30736337, 2019). "HDAC inhibitors are currently FDA-approved for use in some cancers, and thus may be an implementable strategy for treatment of MpBC tumors with high SNAI1 activity." (PMID 31488082, 2019). "Utilization of HDAC inhibitors would require additional profiling of SNAI1 activity and combined targeting of SNAI1 and HDACs might render efficient cancer treatment." (PMID 31165775, 2019). "Interestingly, SNAI1 proteins were physically associated and colocalized with LC3 and SQSTM1 in cancer cells." (PMID 30736337, 2019). "SNAI1 degradation inhibits cancer progression by downregulating many EMT-related proteins." (PMID 30736337, 2019). "These all studies suggest that autophagy might play a key role in controlling the intracellular level of SNAI1, which is essential to determine cell transitions in cancer and hepatocyte differentiation." (PMID 30736337, 2019). "In addition to cancers, autophagy-dependent SNAI1 degradation also determines hepatocyte identity by regulating the transition between EMT and MET." (PMID 30736337, 2019). "In addition, autophagy inhibits the translocation of SNAI1 to the nucleus as well as the migration and invasion of cancer cells, suggesting that degradation of SNAI1 by autophagy is a critical process that controls tumorigenesis." (PMID 30736337, 2019).